DKK1 (dickkopf Wnt signaling pathway inhibitor 1)
Diseases named in the same sentence as DKK1 in open-access papers (continued):
Sharing a sentence is not in itself a finding about the gene and the disease.
bone sarcoma (1 paper, 2015). A sarcoma that arises from the bone. "Our findings that DKK1 and FRP1, two specific antagonists of Wnt signaling at the level of ligand/receptor interactions, caused downregulation of active β-catenin levels and TCF transcriptional activity in bone sarcoma cells, strongly implicated an autocrine Wnt signaling loop." (PMID 25999350, 2015). "However, our findings have identified autocrine Wnt signaling loop in bone sarcomas, providing a novel target for therapeutic intervention with DKK1 and FRP1 antagonists or other modalities and aiming interfering with cell surface interactions involving Wnts and their receptors." (PMID 25999350, 2015).
breast adenocarcinoma (1 paper, 2022). "CBX7 reduces the emergence of breast adenocarcinoma by inhibiting the Wnt/β-catenin pathway via upregulation of the Wnt antagonist DKK-1 expression." (PMID 35464847, 2022).
brucellosis (1 paper, 2019). Brucellosis is a bacterial infection that spreads from animals to people via unpasteurized dairy products or by exposure to contaminated animal products or infected animals. "B. abortus induces the increase of DKK-1 expression in synoviocytes; this is in concordance with the bone resorption observed in patients with osteoarticular brucellosis." (PMID 31695682, 2019).
cartilage tumors (1 paper, 2014). "Expression level of DKK1 and β-catenin accumulation in human cartilage tumors." (PMID 25144498, 2014).
Chlamydia infection (1 paper, 2013). "DKK-1 an inhibitor of wnt signaling has also been shown to alter fibrosis and expression is up-regulated in a Chlamydia infection model." (PMID 23637781, 2013).
cholestasis (1 paper, 2016). Impairment of the bile flow caused by obstruction within the liver, or outside the liver in the bile duct system. "Consistent with our analyses, miR-29a overexpression upregulated Dkk1 protein and maintained Wnt signaling in the quiescent stage of HSC hepatic stellate cells in the livers of the miR-29aTg mice with cholestasis in comparison to their WT littermates." (PMID 26938532, 2016).
Crohn disease (1 paper, 2023). A gastrointestinal disorder characterized by chronic inflammation involving all layers of the intestinal wall, noncaseating granulomas affecting the intestinal wall and regional lymph nodes, and transmural fibrosis. "Dkk1 is increased in the serum and intestinal mucosa of patients with Crohn’s disease, and their levels correlate with those of erythrocyte sedimentation rate and C-reactive protein." (PMID 36730179, 2023).
Encephalocele (1 paper, 2020). A neural tube defect characterized by sac-like protrusions of the brain and the membranes that cover it through openings in the skull. "To explore whether the Wnt pathway plays a role in the treatment effect of MS in TBI, we preinjected DKK-1 (a specific inhibitor of the Wnt pathway that can block the binding between Wnt proteins and cell membrane receptors) into the encephalocele of rats." (PMID 33381552, 2020).
endometrioid carcinomas (1 paper, 2018). "In our series, hypermethylation of the Wnt antagonists (DKK1, DKK2, SFRP1, SFRP4, SFRP5, and WIF1) were observed with a significant prevalence in mucinous and endometrioid carcinomas." (PMID 29882921, 2018).
endotoxemia (1 paper, 2022). "Finally, we find that genetic deletion of DKK1 but not pharmacological neutralization of soluble DKK1 ameliorates inflammation and disease trajectories in a mouse model of endotoxemia." (PMID 36539532, 2022).
Erythema (1 paper, 2015). Redness of the skin, caused by hyperemia of the capillaries in the lower layers of the skin. "Paw erythema and swelling also became more severe with time in control mice than the DKK1 vaccine group." (PMID 26075259, 2015).
essential thrombocythemia (1 paper, 2018). A chronic myeloproliferative neoplasm that involves primarily the megakaryocytic lineage. "In the next step, a quantitative ELISA was used to measure plasma Dkk‐1 levels in 30 young‐onset MPN—10 essential thrombocythemia (ET), 10 polycythemia vera (PV), 10 pre‐fibrotic primary myelofibrosis (pre‐PMF)—and 10 controls." (PMID 29975001, 2018).
Ewing family tumor (1 paper, 2009). "We found increased expression of DKK2 but decreased expression of DKK1 in Ewing family tumor (EFT) cells." (PMID 19247449, 2009).
Fanconi anemia (1 paper, 2018). Fanconi anemia (FA) is a hereditary DNA repair disorder characterized by progressive pancytopenia with bone marrow failure, variable congenital malformations and predisposition to develop hematological or solid tumors. "Interestingly, we previously reported overexpression of DKK1 in cells derived from Fanconi anemia (FA) patients and elevated levels of Dkk1 in blood of FA mutant mice." (PMID 30028084, 2018). "Previous work from our laboratory has demonstrated upregulation of DKK1 in cells and mouse models of the bone marrow failure (BMF) and cancer‐prone disease Fanconi anemia (FA)." (PMID 30028084, 2018).
folate deficiency (1 paper, 2009). A nutritional condition produced by a deficiency of FOLIC ACID in the diet. "In keeping with this, Katula and collaborators showed that folate deficiency led to the downregulation of DKK1, and that MTX inhibited DKK1 transcription." (PMID 19732436, 2009).
gastrointestinal carcinomas (1 paper, 2020). "Patients were diagnosed with gastrointestinal carcinomas, and provided data on the correlation between high and low DKK-1 expression and diagnosis or prognosis." (PMID 33193872, 2020).
gynecological cancer (1 paper, 2021). "The latest findings from clinical trials of anti-DKK1 antibody DKN-01 also demonstrated that DKK1 is a potential candidate for treating advanced GEJ/GC and gynecologic cancers." (PMID 34093545, 2021).
hematoma (1 paper, 2024). A hematoma is a collection of blood from a vascular structure into an extravascular space. "While DKK1 levels strikingly decreased in facture hematoma, we found SOST levels significantly elevated at this early stage of fracture healing." (PMID 38499638, 2024). "As we observed a close inverse correlation of DKK1 and SOST in human fracture hematoma as well as during the fracture healing time course, our data would suggest that also in humans dual inhibition of DKK1 and SOST would most likely be critical to improve fracture healing." (PMID 38499638, 2024).
hemorrhagic stroke (1 paper, 2020). A stroke caused by a bleed on the brain. "Dickkopf‐1 (DKK‐1), an inhibitor of the canonical/‐catenin cascade of the Wnt pathway, was upregulated in brain tissues of hemorrhagic stroke rats, and its rising circulating levels were associated with poor prognosis of acute ischemic stroke patients." (PMID 32324340, 2020).
Hepatic steatosis (1 paper, 2023). Steatosis is a term used to denote lipid accumulation within hepatocytes. "However, hepatic steatosis and lipid accumulation in the AAV-sh-DKK1 group were significantly alleviated." (PMID 36410795, 2023).
hepatitis C virus infection (1 paper, 2022). A viral infection caused by the hepatitis C virus. "In Egyptian patients with hepatitis C virus infection and in Korean patients mostly positive for hepatitis B surface antigen, mean DKK-1 levels showed a two-fold elevation in patients with HCC." (PMID 36230730, 2022).
hip fracture (1 paper, 2023). Traumatic or pathological injury to the hip in which the continuity of either the femoral head, femoral neck, intertrochanteric or subtrochanteric regions is broken. "Another study showed that in patients older than 75 years who sustained a hip fracture, serum SOST and DKK1 levels were significantly higher when compared to healthy controls." (PMID 36768718, 2023).
hyperandrogenism (1 paper, 2019). Excessive secretion of androgens from the adrenal glands or gonads. "In women, genetic variation in DKK1 may result in hyperandrogenism and metabolic dysfunction of PCOS60." (PMID 31745224, 2019).
Hyperinsulinemia (1 paper, 2025). An increased concentration of insulin in the blood. "We speculate that this discrepancy may be due to several factors, including small sample deviation, the influence of sex hormones, or depletion of DKK1‐secreting cells caused by long‐term hyperinsulinemia." (PMID 41320970, 2025). "Our results demonstrated that the DKK1 levels did not change in the normal control group compared to the baseline level under the conditions of normal blood glucose and hyperinsulinemia." (PMID 41320970, 2025).
Hyperkeratosis (1 paper, 2007). Hyperkeratosis is a histopathological term defining a thickened stratum corneum and may be present in many different skin conditions, with many possible overlaps. "Morphologically, the hyperkeratosis was rescued in large part by the addition of soluble, recombinant Dkk1 to the cultures, and this was confirmed by counting the proportion of Ki67-positive basal nuclei." (PMID 17306035, 2007).
Impaired glucose tolerance (1 paper, 2021). An abnormal resistance to glucose, i.e., a reduction in the ability to maintain glucose levels in the blood stream within normal limits following oral or intravenous administration of glucose. "Diabetic mice had highly elevated serum glucose levels and impaired glucose tolerance, regardless of their Dkk1 levels." (PMID 33479403, 2021).
insulinoma (1 paper, 2021). "Mouse insulinoma MIN6 cells were divided into six groups: normal control, low glucose, high glucose, Vehicle, Metrnl, and Dickkopf 1 (DKK1) groups." (PMID 33815109, 2021).
invasive ductal carcinoma (1 paper, 2025). "We also observed that DKK1 was increased in a microarray dataset from invasive ductal carcinoma (IDC) compared to normal breast tissue (GSE897742)." (PMID 39885132, 2025).
keloid (1 paper, 2022). An irregularly shaped, elevated mark on the skin caused by deposits of excessive amounts of collagen during wound healing. "In conclusion, we identified four immune signaling molecules associated with keloid (LGR5, PTN, JAG1, and DKK1)." (PMID 35967426, 2022). "DKK1 has attracted extensive attention as a mechanism for keloid and immune cells." (PMID 35967426, 2022). "Therefore, DKK1 is a promising target for keloid immunotherapy." (PMID 35967426, 2022). "In the GSE7890 dataset, DKK1 and PTN were downregulated in keloid, whereas JAG1 and LGR5 were upregulated in keloid." (PMID 35967426, 2022). "We found that the expression of DKK1 and PTN was downregulated, while the expression of JAG1 and LGR5 was upregulated in keloid." (PMID 35967426, 2022). "Through immunohistochemistry staining, we found that the expression of DKK1 and PTN was lower in the keloid, while JAG1 and LGR5 showed a higher expression in the keloid." (PMID 35967426, 2022). "Finally, four genes related to keloid (LGR5, PTN, JAG1, and DKK1) were identified, and we further studied keloid pathogenesis, which may provide new ideas and insights for keloid treatment." (PMID 35967426, 2022).
kidney (1 paper, 2025). "Evaluation of additional parameters, including histological examinations, inflammatory cytokine level assessments, and immune cell profiling in larger cohorts, may aid in further clarifying the potential role of DKK1 and CKAP4 in kidney transplant rejection." (PMID 40922300, 2025).
kidney cancer (1 paper, 2007). Primary or metastatic malignant neoplasm involving the kidney. "Analysis of DKK1 expression in human cancer specimens revealed DKK1 expression in breast (21 out of 73), lung (11 out of 23) and kidney cancers (six out of 20)." (PMID 17245340, 2007). "In addition, DKK1 could be valuable for detecting lung and kidney cancers, for which no reliable secreted marker is available." (PMID 17245340, 2007).
kidney failure (1 paper, 2023). An acute or chronic condition that is characterized by the inability of the kidneys to adequately filter the blood. "After adjusting for age, sex, baseline eGFR, hemoglobin, albumin, high-sensitivity C-reactive protein and daily urine output, our results revealed that the high serum DKK1 levels (per 100 pg/mL increase) were associated with an increased risk of kidney failure in the CKD patients." (PMID 37108841, 2023).
leiomyoma (1 paper, 2024). A well-circumscribed benign smooth muscle neoplasm characterized by the presence of spindle cells with cigar-shaped nuclei, interlacing fascicles, and a whorled pattern. "In one study, SFRP1 was significantly upregulated in leiomyomas relative to normal adjacent myometrium while other Wnt inhibitors such as APC, DKK1, and DKK3 were significantly downregulated." (PMID 37466765, 2024).
leukopenia (1 paper, 2022). "The rs3782499 in WIF-1 gene was related to fever, leukopenia, and the rs1569198 in DKK-1 was linked to sputum smear-positive in PTB patients." (PMID 36569862, 2022).
lipid metabolism disorders (1 paper, 2025). "Consistent with these, our study found that circulating DKK1 levels may be a better indicator of glucose and lipid metabolism disorders in PCOS women." (PMID 41320970, 2025).
long-bone fracture (1 paper, 2024). "Importantly, when comparing circulating DKK1 levels of these controls to patients immediately upon diagnosis of long-bone fracture, we observed that DKK1 levels were significantly lower in these patients (Median concentration 12.35 pmol/l, P = 0.006, N = 69)." (PMID 38499638, 2024). "In conclusion, with this analysis we can provide preliminary results on the dynamics of DKK1 and SOST after human traumatic long bone fracture." (PMID 38499638, 2024).
metastatic prostate carcinoma (1 paper, 2018). A carcinoma that arises from the prostate gland and has spread to other anatomic sites. "Dickkopf-1 (DKK-1) and sclerostin seem to inhibit osteoblast activity by blocking the Wnt pathway, which leads to progression of metastatic prostate cancer (PC)." (PMID 30116403, 2018).
microcephaly (1 paper, 2025). A congenital or acquired developmental disorder in which the circumference of the head is smaller than normal for the person's age and sex. "For example, DKK1 overexpression in Xenopus embryos caused enlarged anterior head structures, while anti-DKK1 antibody injections led to microcephaly." (PMID 40047162, 2025).
oropharyngeal squamous cell carcinomas (1 paper, 2015). "In summary, our current study showed that DACH1, DKK1, and WIF-1 are methylated in oral and oropharyngeal squamous cell carcinomas." (PMID 25487617, 2015).
osteomyelitis (1 paper, 2023). An acute or chronic inflammation of the bone and its structures due to infection with pyogenic bacteria. "The expression of DKK1 has been recently evaluated in the context of osteomyelitis and infectious processes but as far as we know, there exist no reports of spinal infections." (PMID 36703491, 2023).
pachydermia (1 paper, 2024). "Additionally, DKK1 expression is significantly lower in pachydermoperiostosis fibroblasts compared with normal fibroblasts and enhanced Wnt signalling contributes to the development of pachydermia by promoting DF functions." (PMID 37991164, 2024).
pancreatic endocrine tumour (1 paper, 2009). "Thus, ASCL1 negatively regulates DKK1 and TPH1 in BON1 pancreatic endocrine tumour cells." (PMID 19744316, 2009).
pituitary (1 paper, 2019). "All these findings suggested that FOXP1-induced CLRN1-AS1 suppressed cell growth in pituitary prolactinoma by acting as a ceRNA to regulate the DKK1/Wnt/β-catenin signaling pathway." (PMID 31235696, 2019). "In summary, this study revealed that FOXP1-induced CLRN1-AS1 regulated cellular functions in pituitary prolactinoma by sponging miR-217 to release the DKK1/Wnt/β-catenin signaling pathway." (PMID 31235696, 2019).
plasmacytoma (1 paper, 2007). Plasmacytoma is a localized mass of neoplastic monoclonal plasma cells that represents approximately 5% of all plasma cell neoplasms. "To evaluate the role of mouse Dkk proteins in cancer-associated focal bone lesions in mice, we generated four different sublines of mouse plasmacytoma MOPC315.4 that stably expressed Dkk1, -2, -3 or -4." (PMID 17971207, 2007).
pleura (1 paper, 2017). "The reason why serum DKK1 was slightly lower in pleura metastases group in comparison with non-pleura metastases group may be due to the limited number of patient samples." (PMID 29108326, 2017).
polymyalgia rheumatica (1 paper, 2020). A syndrome characterized by pain, stiffness, and tenderness of the proximal muscle groups including the shoulder, pelvic girdle and the neck. "Currently, data on bone turnover markers (BTM) in polymyalgia rheumatica are scarce, and data on the profile of Dkk-1, sclerostin, and the changes of bone metabolism induced by GC are completely lacking." (PMID 33015101, 2020).
polyp (1 paper, 2024). A usually exophytic mass attached to the underlying tissue by a broad base or a thin stalk. "Significant dysregulation of the expression of critical genes, including DKK1, GPC3, BMP7, FGF17, and WNT10B, was observed in the PPI network; this dysregulation could potentially be associated with the proliferation of polyp tissues." (PMID 38473810, 2024). "DKK1 and DKKL1 showed a significant upregulation in polyp specimens, while WNT10B, GREM1, RSPO3, SFRP5, and GPC3 showed a downward trend." (PMID 38473810, 2024).
reflux esophagitis (1 paper, 2019). "DKK1 secretion has also been associated with increased cellular senescence in other pathologies, such as human reflux esophagitis and in melanocytes, where it promotes the senescent phenotype." (PMID 31083455, 2019).
Schnitzler syndrome (1 paper, 2014). A rare, underdiagnosed disorder in adults characterized by recurrent febrile rash, bone and/or joint pain, enlarged lymph nodes, fatigue, a monoclonal IgM component, leukocytosis and systemic inflammatory response. "Moreover, some rare metabolic diseases such as Schnitzler Syndrome are associated to high DKK1 plasma levels yet higher bone mass." (PMID 25281615, 2014).
scleroderma (1 paper, 2016). Scleroderma is a rare autoimmune connective tissue disorder characterized by abnormal hardening of the skin and, sometimes, other organs. "To assess whether other circulating factors may mediate DKK1 upregulation we treated normal fibroblasts and fibroblasts from patients with scleroderma with serum obtained from patients with SSc (n = 3) prior to and 6 months after RTX treatment." (PMID 27208972, 2016). "We first evaluated the expression of the DKK1 gene in scleroderma compared to normal fibroblasts." (PMID 27208972, 2016). "If indeed this is true and B cells are responsible for the striking lack of Dkk-1 expression in fibroblasts from patients with scleroderma, the next question is how B cells mediate this effect." (PMID 27208972, 2016). "Dkk-1 is strikingly absent from the skin in scleroderma; however, in a subset of patients with SSc, this molecule is upregulated following RTX treatment." (PMID 27208972, 2016).